ACADVL (acyl-CoA dehydrogenase very long chain)
Diseases named in the same sentence as ACADVL in open-access papers:
ACADVL is named in the same sentence as 73 diseases in open-access papers, as found by Europe PMC text mining. Sharing a sentence is not in itself a finding about the gene and the disease. The quoted sentences say what the papers report.
very long chain acyl-CoA dehydrogenase deficiency (17 papers, 2015 to 2025). "A study conducted in Saudi Arabia identified a homozygous c.65C>A (p.Ser22Ter) founder nonsense mutation in exon two of ACADVL in 31 (83.7%) patients with VLCAD deficiency and associated it with an early-onset phenotype." (PMID 40520233, 2025). "Mutations in ACADVL cause the autosomal recessive disorder very long-chain acyl-CoA dehydrogenase deficiency (VLCADD; OMIM #201475), which can manifest as early onset cardiomyopathy, hypoketotic hypoglycaemia, or adult-onset rhabdomyolysis." (PMID 41300791, 2025). "Background: very-long-chain acyl-CoA dehydrogenase deficiency (VLCADD) is caused by two pathogenic mutations in the gene ACADVL, encoding for the enzyme very-long-chain acyl-CoA dehydrogenase." (PMID 41425985, 2025). "Here we present a genetically confirmed case of a South Asian baby girl with severe, early-onset form of very long-chain acyl-coenzyme-A dehydrogenase deficiency due to a novel mutation in ACADVL gene." (PMID 34465376, 2021). "553G>A (p.G185S) and c.1153C>T (p.R385W) in ACADVL confirmed the additional diagnosis of VLCAD deficiency in the proband." (PMID 32655480, 2020). "We identified the heterozygous variant NM_001033859: c.1436 T > C, p.(Pro479Leu) in the ACADVL gene in both parents associated with very long-chain acyl-CoA dehydrogenase deficiency (OMIM #201475)." (PMID 29373990, 2018). "Very long-chain acyl-CoA dehydrogenase deficiency (VLCADD) (OMIM 201475), an autosomal recessive inborn error of metabolism, caused by pathogenic mutations in the ACADVL gene, is a mitochondrial long-chain fatty acid oxidation (lcFAO) disorder." (PMID 32276429, 2020).
cardiomyopathy (9 papers, 2015 to 2025). A disease of the heart muscle or myocardium proper. "This is clearly reflected by the severe clinical symptoms caused by ACADVL deficiency, such as a high incidence of cardiomyopathy in childhood." (PMID 34867990, 2021). "Since deficiencies of either ACADVL or CPT2 can cause cardiomyopathy and arrhythmias in newborns and early infancy, the substantial reduction of FA uptake and oxidation in BTHS hearts likely contributes to the cardiomyopathy phenotype." (PMID 37930434, 2023).
rhabdomyolysis (5 papers, 2018 to 2025). Necrosis or disintegration of skeletal muscle often followed by myoglobinuria. "These intronic nucleotide variations have been previously reported in conjunction with a heterozygous pathogenic missense variant in the ACADVL gene, which is associated with adult-onset exercise-induced rhabdomyolysis." (PMID 40136634, 2025).
heart failure (4 papers, 2018 to 2025). Inability of the heart to pump blood at an adequate rate to meet tissue metabolic requirements. "Cardiopulmonary exercise in heart failure patients was reported to reduce cardiac fibrosis via hypermethylation of acyl-CoA dehydrogenase very long-chain (ACADVL) gene." (PMID 37504569, 2023). "Of note, ACADVL hyperacetylation was also reported in a transverse aortic constriction (TAC)-induced animal model of heart failure, further highlighting the potential role for ACADVL hyperacetylation in metabolic regulation." (PMID 30061171, 2018).
adrenocortical tumors (3 papers, 2015 to 2023). "ACADVL was reported to be associated with the loss of heterozygosity of 17p13 in the pathogenesis of adrenocortical tumors." (PMID 36531021, 2022). "ACADVL expression is downregulated, and ACADVL may be involved in, the pathogenesis of adrenocortical tumors." (PMID 37538114, 2023). "ACADVL expression is down regulated in adrenocortical tumors." (PMID 26620706, 2015).
Obesity (3 papers, 2018 to 2021). Accumulation of substantial excess body fat. "Interestingly, protein expression of ACADVL did not change in our DIO model, suggesting that acetylation may inhibit ACADVL activity and thus contribute to obesity-mediated metabolic dysfunction that contributes to cardiac remodeling and disease." (PMID 30061171, 2018). "Thus, KLF15/PPARα may interact with Sirt3 to regulate Sirt3 activity or expression in response to obesity and thus regulate ACADVL acetylation." (PMID 30061171, 2018).
cardiac hypertrophy (2 papers, 2014 to 2021). "Patients with ACADVL deficiency may present hypertrophy and dilated cardiomyopathy." (PMID 34867990, 2021).
epilepsy (2 papers, 2020 to 2023). A brain disorder characterized by episodes of abnormally increased neuronal discharge resulting in transient episodes of sensory or motor neurological dysfunction, or psychic dysfunction. "ACADVL and HEPHL1 appear to have the weakest association with epilepsy and require further studies." (PMID 37645600, 2023).
leukaemia (2 papers, 2024). "ACADVL overexpression is important to leukaemia mitochondrial metabolism because the loss of ACADVL activity results in the repression of cell proliferation, clonogenic potential, and engraftment in leukaemia cells." (PMID 38843392, 2024).
metabolic myopathy (2 papers, 2015 to 2018). A group of rare inherited disorders characterized by a deficiency of enzymes that are involved in metabolic pathways that affect muscles. "To our knowledge, this is the first description of this disease in dogs, which we propose to name exercise induced metabolic myopathy (EIMM), and the identification of the first canine pathogenic ACADVL variant." (PMID 29491033, 2018).
pancreatic cancer (2 papers, 2023 to 2024). "Another example of an SL interaction predicted by the SL-scan approach is between ACADVL and FABP1 in pancreatic cancer." (PMID 37737478, 2023).
Sepsis (2 papers, 2011 to 2025). Sepsis is defined as life-threatening organ dysfunction caused by a dysregulated host response to infection. "Our team found that the expression levels of ACADVL, AFG3L2, ETFB, PCCB, and PCK2 were significantly overexpressed in ARDS samples compared to sepsis samples (all P value < .05), which was consistent with the results of bioinformatics analysis." (PMID 40068062, 2025).
cardiac arrest (1 paper, 2020). Cessation of breathing and/or cardiac function. "Using WebGestalt algorithms, in the present case, the combination of MYBPC3, TTN, ACADVL, and RYR2 increased significantly the likelihood of cardiac arrest." (PMID 32101375, 2020).
colorectal cancer (1 paper, 2019). A primary or metastatic malignant neoplasm that affects the colon or rectum. "In human, CRNDE knockdown by siRNA in colorectal cancer cell lines leads to an under-expression of FASN, and an overexpression of ACADVL and ACOT9, two genes involved in lipid catabolism." (PMID 31752679, 2019).
COVID-19 (1 paper, 2024). A disease caused by infection with severe acute respiratory syndrome coronavirus 2. "In sum, this study identifies seven lipophagy-related genes (ACADVL, HYOU1, DAP, AUP1, PRXAB2, LSS, and PLIN2) as biomarkers and potential therapeutic targets for COVID-19." (PMID 38932215, 2024). "Seven lipophagy-related genes, including ACADVL, HYOU1, DAP, AUP1, PRXAB2, LSS, and PLIN2, were used as biomarkers and drug targets for COVID-19." (PMID 38932215, 2024). "The lipophagy-related genes ACADVL, HYOU1, DAP, AUP1, PRXAB2, LSS, and PLIN2 can be used as biomarkers and drug targets for COVID-19." (PMID 38932215, 2024). "In the validation set (GSE190496), we observed a significant increase in the gene expression levels of LSS, HYOU1, ACADVL, PRKAB2, PLIN2, AUP1, and DAP in the COVID-19 group compared to the control group." (PMID 38932215, 2024).
essential hypertension (1 paper, 2024). Hypertension that presents without an identifiable cause. "ACADVL was found to be associated with a reduced risk of essential hypertension, nonspecific chest pain, and skin non-epithelial cancer." (PMID 39280009, 2024). "Therefore, targeting ACADVL may be beneficial for patients with T2DM who also suffer from hypertension." (PMID 39280009, 2024).
galactosemia (1 paper, 2021). "However, we found a number of VUS in such known genes, including ACADM, ACADVL and CFTR, and this has also been shown previously for other disease genes included in NBS panels, including PAH gene for phenylketonuria and GALT for galactosemia." (PMID 34449524, 2021).
glycogen storage disease (1 paper, 2025). "Follow-up molecular testing, including ACADVL sequencing, a next-generation glycogen storage disease panel, and a next-generation mitochondrial disease panel (which included several genes for fatty acid oxidation disorders), was unrevealing." (PMID 40745475, 2025).
multiple acyl-CoA dehydrogenase deficiency (1 paper, 2024). "In addition, maternal vitamin B2 deficiency could lead to acylcarnitine and organic acid profiles like those observed in multiple acyl-CoA dehydrogenase deficiency (MIM #231680; ETFA, *608053; ETFB *130410; ETFDH, *231675) or very long chain acyl-CoA dehydrogenase (ACADVL, MIM *609575 #201475)." (PMID 39846587, 2024).
osteosarcoma (1 paper, 2023). A usually aggressive malignant bone-forming mesenchymal neoplasm, predominantly affecting adolescents and young adults. "ATF4 and ACADVL are highly expressed in myeloid cells as well as other cell types, which was suggestive of their roles in osteosarcoma progression." (PMID 37285835, 2023). "In this study, we found significant differences between the prognosis of patients with low and high expression levels of ACADVL, ATF4, HMOX1, INS, and MAPK10, indicating that these genes are potential therapeutic targets of osteosarcoma." (PMID 37285835, 2023). "In the present study, we analyzed the high-throughput RNA-sequencing data and clinical information of 86 osteosarcoma patients, and identified eight prognosis-related genes, including MAP3K5, G6PD, HMOX1, ATF4, ACADVL, MAPK1, MAPK10, and INS." (PMID 37285835, 2023). "However, there are currently no reports on the possible role of ACADVL in osteosarcoma." (PMID 37285835, 2023).
triple-negative breast carcinoma (1 paper, 2025). An invasive breast carcinoma which is negative for expression of estrogen receptor (ER), progesterone receptor (PR), and human epidermal growth factor receptor 2 (HER2). "In triple-negative breast cancer (TNBC), PKM2 upregulates acyl-CoA dehydrogenase very long chain (ACADVL) through the AMP-activated protein kinase–Krüppel-like factor 4 (AMPK–KLF4) axis, promoting lipid β-oxidation while depleting lipid droplet storage." (PMID 40842995, 2025).
tumor (8 papers, 2017 to 2024). "Intra-pancreatic CD8+ T cells from both murine and human tumours showed down-regulation of the very-long-chain acyl-CoA dehydrogenase (ACADVL) enzyme." (PMID 30400822, 2018). "Metabolic reprogramming of tumour-specific T cells through enforced expression of ACADVL enabled enhanced intra-tumoral T cell persistence in an engineered mouse model of PDAC." (PMID 30400822, 2018). "The opposite effects of ACADVL might be driven by the different tumour microenvironments in solid tumours and haematologic tumours." (PMID 38843392, 2024). "Furthermore, ACADVL baseline expression was higher in CCCA tumours (p = 0.001)." (PMID 31892336, 2019). "For example, we identified five lysine acetylation sites in HADHA, four lysine acetylation sites in HADHB, and three lysine acetylation sites in both ACADVL and PCCA, all of which showed lower acetylation levels in tumor tissues." (PMID 33093847, 2020). "The anti-tumor actions of ACOX1, ACAT1, ACADVL, and ACADM were identified as prospective targets." (PMID 37538114, 2023). "A particularly novel finding was that ACADVL baseline expression was the best predictor of both decrease in Ki67 and of low residual Ki67, and its expression was significantly higher in responder and CCCA tumours." (PMID 31892336, 2019).
cancer (6 papers, 2018 to 2025). A tumor composed of atypical neoplastic, often pleomorphic cells that invade other tissues. "Additional contributors such as MAOB and ACADVL have known associations with oxidative signaling and cancer metabolism." (PMID 40941703, 2025). "In the present study, FASN was shown to be upregulated in ACTH-PAs, which was similar to other types of cancer, while enzymes related to fatty acid catabolic metabolism, such as ACADVL, ACADM, and ACAA2, were downregulated in ACTH-PAs." (PMID 30532734, 2018).
infection (4 papers, 2014 to 2023). The state of being infected such as from the introduction of a foreign agent such as serum, vaccine, antigenic substance or organism. "For response to external stimulus annotation, ACADVL, as an acyl-CoA dehydrogenase very long-chain deficiency, is one of the enzymes required for β-oxidation, and mitochondrial β-oxidation can act as a brake to suppress host inflammatory responses in vivo during infection." (PMID 36452142, 2022). "Interestingly, RPL31 and IL8 were almost exclusively expressed after Lena infection, while other genes, including CCL2 and ACADVL, were differentially regulated by infection with both strains, although to different extents." (PMID 24643046, 2014). "However, several other FAO enzymes, such as ACADL, ACADVL, and HADH, showed high levels in response to infection, which supports increased FAO." (PMID 36453897, 2022).
metabolic disorder (4 papers, 2012 to 2024). "Very long-chain acylcarnitine dehydrogenase deficiency (VLCADD) is a rare inherited metabolic disorder associated with fatty acid β-oxidation and characterized by genetic mutations in the ACADVL gene and accumulations of acylcarnitines." (PMID 37367883, 2023). "Very long-chain acyl-coenzyme-A dehydrogenase deficiency is a rare, severe life-threatening metabolic disorder of mitochondrial fatty acid oxidation, caused by mutations in ACADVL gene." (PMID 34465376, 2021).
autosomal recessive inherited disorder (1 paper, 2018). "Deficiency of ACADVL (ACADVLD) in humans is an autosomal recessive inherited disorder with considerable allelic heterogeneity and more than one hundred pathogenic variants in the human ACADVL gene have been reported until now." (PMID 29491033, 2018).
neuromuscular disease (1 paper, 2019). "At 21 years of age, the patient was assessed using a targeted next-generation sequencing-based panel containing 256 neuromuscular disease genes, and found to have a compound heterozygous mutation c.589G > A (p.Val197Met)/c.1742T > C (p.lle581Thr) in the gene (ACADVL, MIM 609565) encoding VLCAD." (PMID 31191348, 2019).
ACADVL also shares sentences with these, for which no sentence is quoted: Hypoglycemia (7 papers); Hepatic steatosis (4); myopathy (4); Insulin resistance (3); pancreatic ductal adenocarcinoma (3); Arrhythmia (2); developmental delay (2); mitochondrial disease (2); Tinnitus (2); alcoholic liver diseases (1); Alstrom syndrome (1); Alzheimer disease (1); cardiac arrhythmias (1); cardiofaciocutaneous syndrome (1); congenital adrenal hyperplasia (1); congenital myopathies (1); diabetes (1); dilated cardiomyopathy (1); hepatocellular carcinoma (1); hereditary hemorrhagic telangiectasia (1); Hyperammonemia (1); hyperlipidemia (1); Hypertension (1); hypertrophy (1); hypospadias (1); idiopathic dilated cardiomyopathy (1); influenza (1); ischemia (1); isovaleric acidemia (1); LCHAD) deficiency (1).
A further 16 diseases each share a sentence with ACADVL in 1 paper.